TMC1 (transmembrane channel like 1)
Description:
Pore-forming subunit of the mechanotransducer (MET) non-selective cation channel complex located at the tips of stereocilia of cochlear hair cells and that mediates sensory transduction in the auditory system (By similarity). The MET complex is composed of two dimeric pore-forming ion-conducting transmembrane TMC (TMC1 or TMC2) subunits, and aided by several auxiliary proteins including LHFPL5, TMIE, CIB2/3 and TOMT, and the tip-link PCDH15 (By similarity). MET channel is activated by tension in the tip-link extending from the side wall of one stereocilium to the tip of the adjacent shorter stereocilium, where the channel is located (By similarity). TMC1 MET channel is highly permeable to calcium and likely transports monovalent cations (By similarity). Also involved in vestibular hair cells transduction current (By similarity).
Synonyms: DFNA36; DFNB11; DFNB7
Tractability: Antibody: UniProt places it where antibodies can reach, with medium confidence; UniProt predicts a signal peptide or a membrane-spanning region; its Gene Ontology location is reachable by antibodies, with medium confidence. PROTAC: ubiquitination databases record sites on it.
Gene: Protein-coding gene on chromosome 9 (72,521,608 to 72,838,297, forward strand). Ensembl gene ENSG00000165091.
Subcellular location: Cell membrane
Pathways (Reactome):
Sensory Perception: Sensory processing of sound by inner hair cells of the cochlea; Sensory processing of sound by outer hair cells of the cochlea
Gene Ontology:
Molecular function: calcium channel activity; mechanosensitive monoatomic ion channel activity; voltage-gated calcium channel activity
Biological process: detection of mechanical stimulus involved in sensory perception of sound; vestibular reflex; calcium ion transmembrane transport; monoatomic ion transmembrane transport
Cellular component: plasma membrane; stereocilium; external side of plasma membrane; membrane; stereocilium tip
Genetic constraint (gnomAD): Loss-of-function variants: 72 observed, 95.86 expected, observed/expected ratio (o/e) 0.75, 90% interval 0.62 to 0.91. The upper end of that interval is the gene's LOEUF score, 0.91, which puts it in group 3 of 6, group 1 being the genes least tolerant of losing a copy. Missense variants: 769 observed, 898.6 expected, observed/expected ratio (o/e) 0.86, 90% interval 0.81 to 0.91. Synonymous variants: 301 observed, 308.12 expected, observed/expected ratio (o/e) 0.98, 90% interval 0.89 to 1.08.
Gene-disease validity (ClinGen):
ClinGen rates the evidence that TMC1 causes each of these diseases.
autosomal recessive nonsyndromic hearing loss 7 (autosomal recessive): Definitive.
nonsyndromic genetic hearing loss (autosomal dominant): Definitive.
Homologues: Orthologues: chimpanzee TMC1 (99% identical), macaque TMC1 (99% identical), dog TMC1 (98% identical), rabbit TMC1 (97% identical), guinea pig TMC1 (96% identical), rat Tmc1 (96% identical), mouse Tmc1 (96% identical), pig TMC1 (95% identical), tropical clawed frog tmc2 (61% identical), zebrafish tmc1 (60% identical), Drosophila melanogaster Tmc (35% identical). Paralogues in human: TMC2 (56% identical), TMC3 (38% identical), TMC7 (20% identical), TMC4 (19% identical), TMC5 (19% identical), TMC8 (18% identical), TMC6 (18% identical).
Diseases named in the same sentence as TMC1 in open-access papers:
TMC1 is named in the same sentence as 26 diseases in open-access papers, as found by Europe PMC text mining. Sharing a sentence is not in itself a finding about the gene and the disease. The quoted sentences say what the papers report.
deafness (86 papers, 2011 to 2026). An inherited or acquired condition characterized by the complete loss of the ability to hear from one or both ears. "Together, these findings provide a structural framework for interpreting deafness-causing mutations in human TMC1 and highlight disulfide-bond-linked hotspots as key molecular determinants of TMC protein biogenesis and trafficking." (PMID 40650136, 2025). "We demonstrate that TMC scramblase is finely tuned by cholesterol, and that three TMC1 deafness-causing mutations with enhanced scramblase activity led to disrupted plasma membrane asymmetry and PS externalization in auditory hair cells." (PMID 40631239, 2025). "Using reconstituted proteoliposomes and molecular dynamics simulations, we demonstrate that both proteins facilitate phospholipid translocation across membrane bilayers, a process tuned by cholesterol and enhanced by deafness-causing TMC1 mutations." (PMID 40631239, 2025). "Analysis of human deafness variant databases revealed multiple missense mutations in this extracellular loop of human TMC1." (PMID 40650136, 2025). "Expanding screening via next-generation sequencing (NGS) to include other established (e.g., MYO15A, OTOF, CDH23, TMC1) and emerging deafness genes would significantly enhance diagnostic yield and capture a broader spectrum of genetic causes." (PMID 41181184, 2025). "TMC1 variants associated with human deafness result in loss of typical MET currents and hair cell senescence, causing cell death." (PMID 38534090, 2024). "The mutation Tmc1 p.D569N (site of a human deafness mutation DFNA36) lies within this interaction range and reduces the maximum MET current, in the present experiments to 0.44 ± 0.19 nA (N = 7)." (PMID 38194445, 2024). "Tmc1 mutation leads to reduced Ca2+ permeability, thus triggering hair cell apoptosis and subsequent deafness." (PMID 39269275, 2024). "TMC1/2 are components of the mechanotransduction channel in hair cells, and mutations of TMC1/2 cause deafness in humans and mice." (PMID 39269275, 2024). "The locus was mapped to human chromosome 9q11-q21 in a region overlapping the DFNB7/11 locus and this new dominant and recessive deafness-caused gene was named TMC1." (PMID 38167128, 2024). "Valuable insights into the pathogenesis of TMC1‐associated deafness have been gained from studies of mutant mice." (PMID 38534090, 2024). "Following GJB2, SLC26A4, MYO15A, OTOF and CDH23, TMC1 is the sixth most common genes causing deafness." (PMID 38167128, 2024). "Both mutations cause dominant human deafness, as does the neighboring Tmc1 p.G411R (using amino acid numbering in mouse)." (PMID 36191207, 2022). "Similar results were achieved in the Baringo mouse, another mouse model of recessive TMC1 deafness caused by a Tyr182Cys point mutation." (PMID 35667089, 2022). "In both mice and humans, dominant and recessive mutations in Tmc1 leading to deafness have been identified." (PMID 36369281, 2022). "As already described, TMC1 was one of the first genes identified as involved in human deafness and was found to be mutated in several murine deafness models." (PMID 35667089, 2022). "Further efforts are needed to analyze other frequent deafness-predisposing genes, such as TMC1, USH2A, CDH23 and MYO15A in an expanded panel in future studies." (PMID 36389375, 2022). "It has been proposed that two mechanisms link pathogenic TMC1 channel variants and deafness: decreased Ca2+ permeability to all pathogenic variants, and decreased resting open probability in low Ca2+ confined to pathogenic dominant variants." (PMID 35407445, 2022). "A 20% reduction in channel amplitude from 58 pS to 46 pS was reported with the deafness-linked mutation Tmie p.R82C/R82C on a Tmc1−/−Tmc2+/+ background, where the wild-type channel conductance is smaller." (PMID 36191207, 2022). "Mutations in the human TMC1 lead to deafness, and deletion of mouse TMC1 removed MET currents in the inner ear hair cells." (PMID 33846502, 2021).
deafness (continued). "We described a new dominant human deafness mutation TMC1 p.T422K and studied the mechanistic consequences in the homologous mouse mutant Tmc1 p.T416K." (PMID 33824189, 2021). "We made four mouse lines harboring Tmc1 point mutations that alter channel properties, causing hair cell degeneration and deafness." (PMID 33824189, 2021). "Three adjacent deafness mutations are TMC1 p.L416R, p.G417R, and p.M418K, the last homologous to the mouse Beethoven that exhibits similar channel effects." (PMID 33824189, 2021). "We report a new dominant human deafness mutation, TMC1 p.T422K, and have characterized the homologous mouse mutant, Tmc1 p.T416K, which caused deafness and outer hair cell (OHC) loss by the fourth postnatal week." (PMID 33824189, 2021). "Here we report a fourth deafness mutation in the same region, TMC1 p.T422K and we generate and characterize the homologous mouse mutation Tmc1 p.T416K." (PMID 33824189, 2021). "There are at least 35 reported point mutations (pathogenic variants) of the TMC1 gene causing human deafness, underscoring the key role of TMC1 in sound transduction." (PMID 33824189, 2021). "The homologous human deafness mutation is TMC1 p.M418K, the mutation site is adjacent to two other missense mutations causing deafness: TMC1 p.L416R and TMC1 p.G417R." (PMID 33824189, 2021). "Regarding TMC1 gene, at least 59 mutations (of the 67 reported in ClinVar) are recessive deafness-causing mutations." (PMID 34778871, 2021). "In this study, by targeted next-generation sequencing of 414 known deafness genes, we identified compound heterozygous mutations p.R34X/p.M413T in TMC1 and p.S3417del/p.R1407T in MYO15A in two recessive Chinese Han deaf families." (PMID 32802042, 2020). "Using targeted next-generation sequencing of 414 known deafness genes, we identified compound heterozygous mutations in TMC1 and MYO15A as the genetic causes of the hearing loss in those families." (PMID 32802042, 2020). "Of the genes misregulated in Mir183/96dko homozygotes, five are known deafness genes; Myo3a, Slc26a5 and Tmc1 underlie deafness in mice and humans, while mutations in Sema3e cause deafness in people, and mice lacking Ocm exhibit progressive hearing loss." (PMID 33318051, 2020). "Three constructs were used for these experiments: enhanced green fluorescent protein (EGFP) as control, wild-type TMC1 (TMC1_WT), and TMC1 deafness (TMC1_dn) that carries a deletion mutation linked to deafness." (PMID 31661074, 2019). "Surprisingly, M412C, which has been linked to deafness in Beethoven mice, behaved like wild-type TMC1." (PMID 31661074, 2019). "Mutations in TMC1 cause human deafness, and double knock-outs of mouse Tmc1/2 result in the loss of MET currents." (PMID 30726219, 2019). "In conclusion, transgenic expression of Tmc2 in mature cochlear HCs partially restored cochlear HC and auditory function in a Tmc1-deficient mouse model of DFNB7/B11 deafness." (PMID 30108230, 2018). "Taken together, the localization of these deafness-causing mutations to the cavity in TMC1 raises the possibility that it functions as an ion permeation pathway." (PMID 30063209, 2018). "The absence or mutation of Tmc1 (deafness and Beethoven mice, respectively) has been shown to prevent the normal progression in hair cell maturation at the onset of hearing, such that they retain immature biophysical properties." (PMID 29093662, 2017). "Key evidence for a role for TMC1 in hair cell transduction is the many mutations of the Tmc1 gene linked to deafness in humans and in mice." (PMID 28983916, 2017). "Tmc1 deficiency in the recessive deafness mouse mutant dn leads to complete deafness and hair cell degeneration, suggesting that Tmc1 is necessary for maturation and survival of hair cells in the murine cochlea." (PMID 23690975, 2013). "TMC1 mutations seem to be rather common causes of recessive deafness in India, Pakistani, Turkish, and Tunisian families." (PMID 23690975, 2013).
deafness (continued). "Interestingly, the D617N mutation displays an intermediate level of PLS activity between wild-type TMC1 and the two dominant mutations, potentially explaining its recessive nature and providing a mechanistic link to the associated deafness phenotype." (PMID 40631239, 2025). "In this study, we show that two dominant (MmTMC1/CmTMC1: M412K/M507K and D569N/D658N) and one recessive (D528N/D617N) deafness-causing mutations enable TMC1 to scramble lipids in the presence of physiological cholesterol levels, resulting in constitutive externalization of PS." (PMID 40631239, 2025). "TMC1 is one of the most common deafness genes causing DFNA36." (PMID 38167128, 2024). "Besides T416K (human TMC1 p.G4226R) and the M412K (human TMC1 p.G418K), there are two other neighboring human deafness mutations, TMC1 p.G416R and TMC1 p.L417R, the functional effects of which in mice would be worth studying." (PMID 33824189, 2021). "A mutation in TMC1-expressing inner ear cells causes deafness." (PMID 34429071, 2021). "TMC1 is required for the normal functioning of cochlear hair cells, and its mutations have been associated with progressive postlingual hearing loss and profound prelingual deafness." (PMID 34454438, 2021). "Interestingly, in the Beethoven (Bth) mouse model of deafness, hearing loss is caused by a missense Tmc1 mutation (p.M412K, c.T1235A) and follows a dominant mode of inheritance." (PMID 34778871, 2021). "There were reports that variants in HOMER2 and TMC1 genes may cause autosomal dominant non-syndromic deafness." (PMID 32487028, 2020). "It has been reported that mutations in TMC1 may cause both prelingual profound autosomal recessive deafness DFNB7/11 and postlingual progressive autosomal dominant deafness DFNA36." (PMID 32802042, 2020). "The most frequent causative deafness gene was TMC1 (DFNA36) (3 cases), followed by the next tier of genes (2 cases each) (CDH23, COCH, SLC26A4, TMPRSS3, ATP1A3), and the genes that were detected only once (ACTG1, GJB2, ILDR1, MYO7A, MYO15A, NF2, NLRP3 and SERPNB6)." (PMID 32238869, 2020). "Mutations in the mechanotransduction channel component TMC1/2 cause deafness." (PMID 30670701, 2019). "Mutations in Tmc1/TMC1 cause both dominant and recessive forms of deafness in mice and humans." (PMID 30670701, 2019). "In this study, we sought to test the hypothesis that persistent Tmc2 expression could substitute for loss of Tmc1 expression in mature cochlear HCs in a mouse model of Tmc1-deficient deafness." (PMID 30108230, 2018). "Finally, the deafness-causing TMC1 Beethoven (Bth) mutation (M418K in hTMC1 or M412K in mTMC1) alters the Ca2+ permeability, single channel conductance and dihydrostreptomycin blockade of the MET channel." (PMID 30063209, 2018). "In addition, many mutations in TMC1 that cause deafness localize near the peripheral cavity, with several lining the putative permeation pathway." (PMID 30063209, 2018). "Indeed, mutations in TMC1 cause deafness in humans and inner ear hair cells from double knock-out mice for Tmc1 and Tmc2 have no MET currents." (PMID 24957570, 2015). "However, whether gene therapy for TMC1 mutation-caused deafness is available for human beings remains unknown." (PMID 38167128, 2024). "We have extended that work using the CRISPR/Cas9 technology to generate mice with missense mutations in TMC1, which enabled us to characterize the deafness phenotype, whether dominant or recessive, and possible mechanism relating to hearing loss in the unaltered endogenous tissue." (PMID 33824189, 2021). "Intriguingly, LGR6 can also chaperon the deafness-related TMC1 mutants, including M412K (Beethoven) and D569N, to the plasma membrane of HEK293 cells." (PMID 39966628, 2025). "Preclinical studies in murine models of deafness—including Otof−/−, Tmc1−/−, and Tmprss3 mutants—have demonstrated the potential of AAV vectors to restore auditory function by rescuing defective genes." (PMID 40792200, 2025).
deafness (continued). "Our conclusion is opposite to that previously suggested, which was largely based on the reduced MET channel Ca2+ permeabilities of Tmc1 deafness mutants that initiate scramblase activity." (PMID 40100636, 2025). "It has been found that TMC1 knockout mice exhibit complete deafness but retain vestibular function, partly because TMC2 continues to be expressed in vestibular hair cells." (PMID 41049429, 2025). "Tmc1−/− mice were used as a model of TMC1 recessive deafness in a study in which the Tmc1 coding sequence was delivered by injection of AAV at P1 to alleviate hearing loss." (PMID 35667089, 2022). "Even though hair cells harboring the Tmc1 mutations exhibited MET currents in the first few postnatal days, all mutations eventually led to loss of transduction and deafness by P30." (PMID 36191207, 2022). "In a recent study, the Anc80L065 vector encoding Tmc1 was also used to rescue hearing and vestibular phenotypes of DFNB7/11 recessive deafness mouse model." (PMID 33507440, 2021). "Transmembrane channel-like protein isoform 1 (TMC1) is a major component of the mechano-electrical transducer (MET) channel in cochlear hair cells and is subject to numerous mutations causing deafness." (PMID 33824189, 2021). "While some variants are prevalent in certain populations, such as GJB2 167delT in Ashkenazi Jews and TMC1 p.Ser647Phe in Moroccan Jews, many of the deafness genes affect only a handful of families." (PMID 33350593, 2021). "After exclusion of the three most frequently mutated deafness genes in Tunisia: GJB2, TMC1, and SLC26A4 genes, ES was carried out for the index case TNDF182-3." (PMID 34614013, 2021). "In humans and mice, mutation of transmembrane channel-like 1, TMC-1 is known to cause dominant and recessive forms of deafness." (PMID 32228447, 2020). "In particular, among the three patients carrying the same TMC1 variant (p.Asp572Asn), SB144-238 with deafness duration of approximately 20 years demonstrated the K-CID, spondee, and PB word scores of 16, 30, and 16.66, respectively at 1-year evaluation." (PMID 32238869, 2020). "We made a mouse mutation, Tmc1 p.D569N, homologous to a human DFNA36 deafness mutation, which also had MET channels with lower Ca2+‐permeability but showed better fast adaptation than wild‐type Tmc1+/+ channels." (PMID 31633194, 2019). "The variants of TMC1, ESPN, POU3F4, MYH14, EYA1, and MR-RNR1 genes followed those from the top tier deafness genes in the order of frequency as a molecular etiology of severe-to-profound NSHL in Vietnamese." (PMID 30733538, 2019). "In this study, 48.5% (16/33) families were detected the pathogenic variants in eight known deafness genes, including 10 novel variants identified in TMPRSS3 (MIM 605551), MYO15A (MIM 602666), TMC1 (MIM 606706), ADGRV1 (MIM 602851), and PTPRQ (MIM 603317)." (PMID 31379920, 2019). "(C) Representative traces showing the rescue of leak conductance in OHCs by control full-length TMC1 (TMC1_WT), deafness TMC1 (TMC1_dn), TMC1-G411C (G411C), TMC1-M412C (M412C), TMC1-N447C (N447C), TMC1-D528C (D528C), TMC1-T532C (T532C), and TMC1-D569C (D569C)." (PMID 31661074, 2019). "Prior work showed that, during postnatal maturation, outer HCs fail to acquire a slow delayed rectifier outward potassium current, Ik,n, in Tmc1 mutant (deafness) mice." (PMID 30108230, 2018). "Three out of six mutants (p.E64D, p.F91S, and p.C99W) affected interactions of CIB2 with TMC1 (bottom), suggesting that these mutations disrupt the putative TMC1-CIB2 complex in hair cells and thus cause deafness in humans." (PMID 28663585, 2017). "The human Tmc1 is a major deafness gene, and mouse Tmc1 is required together with its paralogue Tmc2 for cochlear hair cell mechanotransduction." (PMID 25053538, 2015). "Of them, 9 deafness genes expressed more in the apical turn (Pou4f3, Slc17a8, Tmc1, Crym, Otof, Ush1c, Pcdh15, Slc26a5, and Lhfpl5) and six were internal controls (Gapdh, Actb, Rps17, Rpl30, Atp6, and Ipo8)." (PMID 24676347, 2014).